MDM2 (MDM2 proto-oncogene)
Diseases named in the same sentence as MDM2 in open-access papers (continued):
Sharing a sentence is not in itself a finding about the gene and the disease.
neuroblastoma (continued). "Our results confirm a smaller retrospective study analyzing MDM2 expression in 91 primary neuroblastomas, in which MDM2 expression negatively correlated with event-free survival after three years." (PMID 29416773, 2018). "We provide the first preclinical feasibility study of the novel orally available MDM2 antagonist DS-3032b in neuroblastoma." (PMID 29416773, 2018). "We assessed the effect of the novel small molecule MDM2 inhibitor, DS-3032b, on several hallmarks of cancer in a panel of six neuroblastoma cell lines with varying genetic backgrounds." (PMID 29416773, 2018). "Here, we report that high-level MDM2 expression signals an unfavorable prognosis in a cohort of 476 primary neuroblastomas and correlates with clinical and molecular characteristics of unfavorable tumor biology." (PMID 29416773, 2018). "We reanalyzed microarray expression data from a cohort of 476 primary neuroblastomas to assess correlations between MDM2 expression and patient prognosis." (PMID 29416773, 2018). "Within stage 4 neuroblastoma, correlation between MDM2 expression and poor event-free and overall survival is present in MYCN non-amplified tumors, but not in MYCN amplified tumors." (PMID 29416773, 2018). "For neuroblastoma cells, MDM2 inhibitors cooperate with anaplastic lymphoma kinase (ALK) inhibition." (PMID 30206211, 2018). "In neuroblastoma, reports have mainly been limited to chemotherapeutics that enhance the efficacy of MDM2 antagonists." (PMID 28915653, 2017). "This interspecies selectivity hampers the use of murine transgenic models for the in vivo evaluation of MDM2 antagonists and prompted us to use a well-established model system utilizing orthotopic neuroblastoma xenografts." (PMID 28915653, 2017). "In this study, we assessed the antitumor activity of ceritinib in combination with NVP-CGM097, a potent and selective small molecule inhibitor of MDM2, in ALK-mutated or ALK-amplified neuroblastoma models." (PMID 28425916, 2017). "The potential therapeutic benefit for neuroblastoma has been evaluated in phase II-like trials with recent MDM2 inhibitors that have entered in clinical evaluation for adult cancers." (PMID 28673313, 2017). "These biological conditions appear to make neuroblastoma cells highly sensitive to treatment with MDM2 antagonists." (PMID 28915653, 2017). "Small molecule MDM2 antagonists represent a potential novel therapeutic strategy for neuroblastoma treatment." (PMID 28915653, 2017). "In conclusion, these data strongly support the further evaluation of dual BCL2/MDM2 targeting as a therapeutic strategy in neuroblastoma." (PMID 28915653, 2017).
neuroblastoma (continued). "(ii) The ARF–MDM2 axis is frequently hit in neuroblastoma cells via direct genetic and epigenetic targeting, eventually resulting in high MDM2 activity." (PMID 23091802, 2012). "Although the Shh target NMyc binds to the Mdm2 gene and directly regulate Mdm2 transcription in neuroblastoma cell lines we find that the level of total Mdm2 mRNA is not significantly increased following Shh stimulation of GNPs." (PMID 21437245, 2011).
neuroblastoma (continued). "Clinical trials assessing MDM2 inhibition in neuroblastoma are ongoing (NCT03654716, NCT03611868)." (PMID 37835416, 2023). "Inhibition of MDM2 suppresses the progression of MYCN-dependent neuroblastoma." (PMID 35655142, 2022). "Quite the contrary, MYCN induces MDM2 expression in neuroblastoma cells." (PMID 34832966, 2021).
neuroblastoma (continued). "To assess the increased expression of MDM2 mRNA in response to CHK1i, we performed RT-qPCR analysis in seven neuroblastoma cell lines: NB-39-nu, SMS-SAN, NBLS, CHP134, SH-SY5Y, SK-N-AS, and SK-N-BE treated with 1 and 5 μM PF-477736 for 24 hours or without PF-477736." (PMID 33014050, 2020). "Therefore, targeting MDM2 provides a promising approach to neuroblastoma therapy, especially for advanced disease." (PMID 33291373, 2020). "Overall, these studies suggest MDM2 is a potential target for anticancer therapy in neuroblastoma." (PMID 33291373, 2020). "In addition, elevated MDM2 expression has also been found to promote multidrug resistance in neuroblastoma cells." (PMID 33291373, 2020). "In particular, MDM2 stabilizes mRNA of vascular endothelial growth factor (VEGF) by binding directly to 3’ UTR of the mRNA, thus in turn causes the increased translation of VEGF, contributing to the growth of neuroblastoma under hypoxia condition." (PMID 33291373, 2020). "MDM2 is amplified in a variety of malignancies, including neuroblastoma." (PMID 33291373, 2020). "Collectively, CEP131 may have prognostic potential for unfavorable neuroblastoma patients and be negatively regulated by MDM2 in neuroblastoma." (PMID 33014050, 2020). "MDM2 haploinsufficiency inhibits tumor formation in a MYCN-driven neuroblastoma mouse model." (PMID 29416773, 2018). "CRISPR-mediated MDM2 knockout in neuroblastoma cells mimicked DS-3032b treatment." (PMID 29416773, 2018). "Also, we validated the interaction between endogenous NGFR and MDM2 in human neuroblastoma SK-N-SH cells that sustains high level of NGFR." (PMID 27282385, 2016).
neuroblastoma (continued). "Interestingly, ARF inactivation (due to deletions or promoter methylation) or MDM2 amplification are frequently found in neuroblastoma cell lines." (PMID 23091802, 2012). "In addition, combining MDM2 antagonists with other drugs or experimental compounds has the potential to enhance therapeutic outcomes and offer a more effective treatment strategy, ultimately leading to reduced relapse rates in neuroblastoma patients." (PMID 39802403, 2025).